ENSG00000265690 (novel protein)
Gene: Protein-coding gene on chromosome 16 (67,163,385 to 67,165,815, forward strand). Ensembl gene ENSG00000265690.
Genetic constraint (gnomAD): Missense variants: 241 observed, 165.87 expected, observed/expected ratio (o/e) 1.45, 90% interval 1.31 to 1.62. Synonymous variants: 110 observed, 80.79 expected, observed/expected ratio (o/e) 1.36, 90% interval 1.17 to 1.6.